FBLN1 (fibulin 1)
Diseases named in the same sentence as FBLN1 in open-access papers (continued):
Sharing a sentence is not in itself a finding about the gene and the disease.
bladder cancer (continued). "Altogether, our results indicated that fibulin-1 expression is associated with NMIBC grade and recurrence, it is epigenetically down-regulated and functions as a tumor suppressor gene and angiogenesis inhibitor in bladder cancer." (PMID 25234557, 2014). "Fibulin-1, a multi-functional extracellular matrix protein, has been demonstrated to be involved in many kinds of cancers, while its function in bladder cancer remains unclear." (PMID 25234557, 2014). "Here we report that fibulin-1 expression is associated with NMIBC grade and recurrence, it is epigenetically down-regulated and functions as a tumor suppressor gene and angiogenesis inhibitor in bladder cancer." (PMID 25234557, 2014). "Implying that the expression of fibulin-1 in muscle-invasive bladder cancer tissues might be different." (PMID 25234557, 2014). "miR892b modulates the FBLN1, MYH7B and MST1R genes and is known to influence proliferation, migration, and invasion of bladder cancer cells." (PMID 34357026, 2021). "Firstly, the expression levels of fibulin-1 in 4 bladder cancer cell lines (5637, HT1376, J82 and T24) and a non-tumorigenic bladder cell line SV-HUC-1 were evaluated by qPCR and Western blot respectively." (PMID 25234557, 2014).
Stroke (5 papers, 2019 to 2025). Sudden impairment of blood flow to a part of the brain due to occlusion or rupture of an artery to the brain. "Both male and female MMP-3 KO stroke brains showed decreased expression of genes involved in fibulin signaling (Fbln1, Fbn1, Fbln2, Fbln5), which are known to induce EMT during embryonic development." (PMID 39000490, 2024). "Key EMT-related genes that were downregulated upon MMP-3 KO in male stroke brains included Fbn1, Fbln1, Tgfb1, Tgfbr3, Snai2, and Fgf2." (PMID 39000490, 2024). "Key EMT-related genes that were downregulated in female MMP-3 KO stroke brains included Fbln5, Fbln1, Fbln2, and Tgfb1." (PMID 39000490, 2024). "Some of the stroke subtype-specific proteins (FBLN1, F2, SERPINF2, CBP2, FCN3, GPX3, IKG, and GSN) were also affected by the CBS deficiency." (PMID 31242583, 2019). "Key EMT-related genes that were downregulated in MMP-3 KO males included Fbn1, Fbln1, Tgfb1, Tgfbr3, Snai2, and Fgf2, while female MMP-3 KO stroke brains showed downregulation of Fbln5, Fbln1, Fbln2, and Tgfb1." (PMID 39000490, 2024). "Based on our data, we suggest that CPN2, FXII, PLG, MASP1, APCS, PON1, and CA1 for IS and FBLN1 and GRN for ICH should be further scientifically pursued as potential stroke blood biomarkers." (PMID 34975707, 2021). "Fibulin-1, as an ECM protein, was found to be significantly upregulated in CAD as compared to stroke subjects in this study." (PMID 32508734, 2020). "Likewise, while our analysis identified SPOCK1 and BCAN as ECM-related markers, other studies found ECM proteins like fibulin-1, fibronectin, and MMP9 elevated in stroke, highlighting consistent engagement of tissue remodeling pathways across stroke types." (PMID 41152969, 2025).
aortic valve stenosis (4 papers, 2012 to 2025). Aortic valve stenosis (AVS) is a condition characterized by narrowing of the heart's aortic valve opening. "The aim of this study was to investigate whether fibulin-1 was associated with NT-proBNP, suPAR and echocardiography measures in patients with mild to moderate aortic valve stenosis before and during lipid-lowering treatment." (PMID 25014213, 2014).
breast tumors (4 papers, 2003 to 2022). "(b) FBLN-1 is also found to be a pro-immunogenic glycoprotein involved in interactions between dendritic cells and cytotoxic T cells, and the high expression is linked to better lymphoid infiltration of breast tumors." (PMID 36361532, 2022). "We also sought to correlate fibulin-1 expression levels with the oestrogen receptor status of the breast tumour specimens." (PMID 12644824, 2003). "In summary, these results provide evidence for elevated expression and altered processing of fibulin-1 protein in breast tumour development and progression." (PMID 12644824, 2003). "Overall, fibulin-1 processing was more extensive in the ER/PR-positive as compared to ER/PR-negative breast tumour cell lines." (PMID 12644824, 2003). "In this study, we evaluated fibulin-1 protein expression in human breast tumours." (PMID 12644824, 2003). "If the observed fragments are derived by proteolysis of mature fibulin-1 polypeptide, it is reasonable to hypothesise that the altered processing of fibulin-1 is reflective of differential proteinase activity in the breast tumours." (PMID 12644824, 2003). "In fact, in tumor extracellular matrix proteomic analysis from breast tumors, THBS2, followed by FBLN1 and COL1A1, have the highest correlation with collagen fiber alignment, an ECM trait predictive of shorter disease-free survival." (PMID 35159353, 2022). "Full-length fibulin-1 protein was detected in the CCM, but not in the cell extract of the six human breast tumour-derived cell lines analysed." (PMID 12644824, 2003).
chronic kidney disease (4 papers, 2013 to 2025). Impairment of the renal function secondary to chronic kidney damage persisting for three or more months. "Other studies have indicated that fibulin-1 plays a role in cardiac and vascular remodeling in chronic kidney disease." (PMID 40564116, 2025). "Plasma fibulin-1 was determined in subjects with chronic kidney disease (n = 32; median age 62.5, inter-quartile range 51 – 73 years) and 60 age-matched control subjects." (PMID 23294625, 2013). "Compared to control subjects, patients with chronic kidney disease showed higher fibulin-1 levels (p < 0.001)." (PMID 23294625, 2013).
chronic obstructive pulmonary disease (4 papers, 2018 to 2024). A chronic and progressive lung disorder characterized by the loss of elasticity of the bronchial tree and the air sacs, destruction of the air sacs wall, thickening of the bronchial wall, and mucous accumulation in the bronchial tree. "The genetic inhibition of FBLN1 decreases the inflammatory cells by reducing pro-inflammatory cytokines within chronic obstructive pulmonary disease and its expression increases infiltrating macrophages by elevating the stromal and immune scores in high FBLN1 tissues." (PMID 36744248, 2023).
colorectal cancer (4 papers, 2015 to 2025). A primary or metastatic malignant neoplasm that affects the colon or rectum. "In addition, the serum fibulin-1 level has been found to be significantly lower in colorectal cancer patients than in patients with benign colon polyps or healthy individuals." (PMID 41301725, 2025). "In addition, in colorectal cancer cells, and in fibroblasts it decreases the expression of fibulin-1, a matrix protein that characterizes normal intestinal tissue —the reduced expression allows colorectal cancer to develop." (PMID 37408240, 2023). "However, the role of FBLN1 in colorectal cancer (CRC) has not been examined." (PMID 25837757, 2015).
fibrosarcoma (4 papers, 2003 to 2023). A malignant mesenchymal fibroblastic neoplasm affecting the soft tissue and bone. "The expression of fibulin-1 is low in many tumor-derived cell lines, and exogenous fibulin-1 (fibulin-1D) suppresses cell growth and invasion in human fibrosarcoma, suggestive of its inhibitory role for tumorigenesis." (PMID 30227601, 2018). "The extracellular matrix protein fibulin-1 suppresses the motility and invasiveness of a variety of tumour cell types in vitro as well as the growth of fibrosarcoma tumours in nude mice." (PMID 12644824, 2003). "However, the elevated expression level of FBLN1 in fibrosarcoma-derived cells has demonstrated inhibition of tumor formation in nude mice as well as invasion in the gels of reconstituted basement membrane extracts." (PMID 37719007, 2023).
renal cell carcinoma (4 papers, 2017 to 2023). "Expression of fibulin-1 is decreased in renal cell carcinoma and suppresses progression of cancer." (PMID 37250906, 2023).
Aortic dissection (3 papers, 2009 to 2020). Aortic dissection refers to a tear in the intimal layer of the aorta causing a separation between the intima and the medial layers of the aorta. "Age-related elastin fragmentation and medial degeneration are the hallmarks of aortic stiffness leading to aortic dissection, which presumably explains the parallel loss of fibulin-1." (PMID 29867203, 2018). "Therefore, a downregulation of fibulin-1 expression may contribute to the development of aortic dissection, either by weakening the aortic connective tissue or by altering the cellular signal transduction." (PMID 19652764, 2009).
cardiomyopathy (3 papers, 2013 to 2023). A disease of the heart muscle or myocardium proper. "Fibulin-1 mRNA expression is increased in a model of cardiomyopathy, and fibulin-1 plasma levels positively correlate with plasma N-terminal pro-B-type natriuretic peptide, a cardiac marker of pressure or volume overload." (PMID 23294625, 2013). "Fibulin-1 has been shown to regulate lung remodeling in mouse models of pulmonary disease and upregulation of fibulin-1 has been observed in a mouse model of cardiomyopathy suggesting a role for this protein in tissue regeneration." (PMID 36506087, 2022).
endometriosis (3 papers, 2022 to 2023). The growth of functional endometrial tissue in anatomic sites outside the uterine body. "Recently, Fibulin 1 (FBLN1) has been discovered as a key ferroptosis-resistant candidate molecule in endometriosis." (PMID 37296777, 2023). "Conversely, inhibition of fibulin-1 increased ferroptosis within endometriotic stromal cells, suggesting a potential therapeutic strategy for endometriosis." (PMID 37638130, 2023).
fibrosis (3 papers, 2021 to 2026). the formation of excess fibrous connective tissue in an organ or tissue in a reparative or reactive process. "To examine whether serum Fibulin-3 and Fibulin-1 levels change with advanced fibrosis in another cohort, we measured the serum Fibulin-3 and serum Fibulin-1 levels in cohort 2 (473 patients with MASLD with biopsy)." (PMID 38829196, 2024). "In addition, serum Fibulin-3 and serum Fibulin-1 levels changed significantly with advanced fibrosis." (PMID 38829196, 2024). "According to bibliography, even though FBLN1 mRNA levels may decrease in COPD where small airway fibrosis occurs, on the protein level it is accumulated in the ECM." (PMID 33826640, 2021). "The serum Fibulin-3 concentration was greater in patients with advanced fibrosis than in patients with nonadvanced fibrosis, with no change in the serum Fibulin-1 concentration between patients with advanced and nonadvanced fibrosis." (PMID 38829196, 2024). "Using another cohort with biopsy, we found that the serum Fibulin-3 concentration was significantly greater in those with advanced fibrosis but that the serum Fibulin-1 concentration was not significantly different." (PMID 38829196, 2024). "Among these 3 proteins, Fibuiln-3 and Fibulin-1 were significantly different between patients with advanced and nonadvanced fibrosis (Mann-Whitney U test p<0.05)." (PMID 38829196, 2024).
glioma (3 papers, 2015 to 2021). A benign or malignant brain and spinal cord tumor that arises from glial cells (astrocytes, oligodendrocytes, ependymal cells). "An interaction between angiogenin and fibulin-1 could provide one possible mechanism behind the increased proliferation we observed when glioma cells were grown on matrix generated by hypoxic astrocytes." (PMID 33802060, 2021). "It was validated that fibulin-1 was highly expressed on the surface of human gliomas and it might be involved in the aggressive nature of tumors." (PMID 28736531, 2017). "But no details about the roles of FBLN1 in gliomas have been reported previously." (PMID 25866482, 2015).
heart failure (3 papers, 2014 to 2025). Inability of the heart to pump blood at an adequate rate to meet tissue metabolic requirements. "In the present study, we found that decreased plasma FBLN1 level could lead to the impairment of renal function, which is counterintuitive and suggests that, like BNP in heart failure, increased FBLN1 may be a compensatory result when renal function is impaired." (PMID 39329105, 2024).
ischemic stroke (3 papers, 2019 to 2023). A stroke disorder caused by obstruction of blood flow to the brain, due to thrombotic (local blood clot formation) or embolic (due to a blood clot or other material traveling from another site) event. "Six candidate proteins (LBP, VCAM1, FCN2, FBLN1, APOC-I, and APOB) were assessed using individual samples from the CAD and non-CAD ischemic stroke subjects." (PMID 32508734, 2020). "For the first time, differential expressions of apolipoprotein B, apolipoprotein C-I, lipopolysaccharide-binding protein, vascular cell adhesion molecule 1, fibulin-1, and ficolin-2 were confirmed as being significantly upregulated in CAD as compared to non-CAD ischemic stroke subjects." (PMID 32508734, 2020).
liver fibrosis (3 papers, 2011 to 2025). "While only scarce information is available about versican in fibrosis, except in the lung (where it may influence early repair processes), fibulin-1 deposits were already reported in rat liver fibrosis." (PMID 21975223, 2011).
melanoma (3 papers, 2022 to 2025). A malignant, usually aggressive tumor composed of atypical, neoplastic melanocytes. "We defined clusters corresponding to melanoma (PMEL, MLANA), immune infiltrates (TRBC2, TRAC, TMSB4X), melanophages (CD74, LYZ), keratinocytes (KRT14, TRIM29), blood vessels (CAVIN1, PECAM), and fibroblast‐enriched areas in the dermis (DCN, COL1A2, FBLN1)." (PMID 39846232, 2025).
Myocardial fibrosis (3 papers, 2012 to 2021). "This hypothesis that fibulin-1 reflects asymptomatic myocardial fibrosis that is not accompanied by LV hypertrophy and/or reduced ejection fraction, give rise to the possibility that fibulin-1 may add prognostic information to the current echocardiographic follow-up in these patients." (PMID 25014213, 2014).
non-small cell lung carcinoma (3 papers, 2020 to 2025). A group of at least three distinct histological types of lung cancer, including non-small cell squamous cell carcinoma, adenocarcinoma, and large cell carcinoma. "Song Wei and associates identified that the concentrations of cathepsin F (CTSF) and Fibulin-1 are elevated in the serum and tissue of non-small cell lung cancer (NSCLC) patients with brain metastases, in contrast to patients without brain metastases or individuals with primary brain tumors." (PMID 39791166, 2025). "Fibulin-1 (FBLN1) is a major component of the ECM in lung tissue, and its levels are known to be downregulated in non-small cell lung cancers (NSCLC)." (PMID 32719793, 2020).
virus infection (3 papers, 2024 to 2025). "The importance of the increase in fibulin-1 in EBV infection has not been fully understood, although the protein’s influence in other viral infections, including oncogenic papillomavirus E6, has been confirmed." (PMID 38921769, 2024).
arteriosclerosis (2 papers, 2012 to 2014). A vascular disorder characterized by thickening and hardening of the walls of the arteries. "In the present study, significant differences in fibulin-1 levels between patients with or without known arteriosclerosis were not established, but still we find associations between fibulin-1 and measures of restrictive filling pattern." (PMID 23316326, 2012).
brain tumors (2 papers, 2022 to 2025). "Thirdly, on ROC curve analysis, a combination of CTSF and FBLN1 was found to effectively discriminate NSCLC BM cases from NSCLC and primary brain tumours cases." (PMID 35217799, 2022). "The clinical value of CTSF, FBLN1, and AKR1B10 in the diagnosis of NSCLC BM was assessed in cohort 2 comprising of 459 patients including 379 patients with NSCLC, 30 primary brain tumours (PBT), and 50 HG." (PMID 35217799, 2022). "FBLN1 was also expressed in a certain proportion of lung tissues; however, it was not commonly expressed in other brain tumours." (PMID 35217799, 2022). "Secondly, the expressions of CTSF and FBLN1 in NSCLC BM tissues were significantly higher than those in NSCLC without BM and other primary brain tumour tissues, although the expression of FBLN1 in tumour cells was relatively weak." (PMID 35217799, 2022).
chronic lung disease (2 papers, 2015 to 2023). According to the definitions of the American and British Thoracic Societies, including pulmonary functional tests, X-rays, and CT scans for items such as fibrosis, bronchiectasis, bullae, emphysema, nodular or lymphomatous abnormalities. "Ongoing investigation of the role of fibulin-1 may reveal the mechanisms underlying the pathphysiology of chronic lung diseases." (PMID 25834989, 2015).
Cirrhosis (2 papers, 2020 to 2024). A chronic disorder of the liver in which liver tissue becomes scarred and is partially replaced by regenerative nodules and fibrotic tissue resulting in loss of liver function. "They discovered that extracellular vesicle-specific proteins such as thrombospondin-1, fibulin-1, and fibrinogen gamma chain could distinguish between healthy volunteers and patients with cirrhosis and HCC." (PMID 38541004, 2024). "Importantly, the Fibulin-1 levels were also increased in patients with HCC (54.51 ± 73.47) compared with that in patients with cirrhosis (22.93 ± 16.87) and that in patients with chronic hepatitis B (11.53 ± 10.76)." (PMID 32612994, 2020).
Diabetic Nephropathy (2 papers, 2021 to 2025). "Furthermore, fibulin-1 may serve as a potential therapeutic target in diabetic nephropathy." (PMID 40564116, 2025).
glaucoma (2 papers, 2011 to 2024). Increased pressure in the eyeball due to obstruction of the outflow of aqueous humor. "Also related to “ECM organization”, were 3 other genes (Fbln1, Fn1, and Loxl1) known to be associated with different types of glaucoma." (PMID 38272861, 2024). "FBLN1 was recently discovered as a downstream target of SP1 transcription factor (SP1) in a manuscript regarding the network analysis of human glaucoma." (PMID 21655357, 2011).
Marfan syndrome (2 papers, 2009 to 2021). A disorder of the connective tissue. "For example, Marfan syndrome and Ehlers-Danlos syndrome are known to cause vascular fragility due to mutations in the FBLN1 and COL3A1 genes associated with elastic and collagen fibers, leading to aortic aneurysms and AD." (PMID 35008739, 2021). "We conclude that the downregulation of fibulin-1 and/or of decorin in AAD patients could be an alternative molecular mechanism—opposed to a mutation in fibrillin-1 as seen in patients suffering from Marfan syndrome—leading to the same or similar phenotype." (PMID 19652764, 2009).
mesothelioma (2 papers, 2015 to 2022). A usually malignant and aggressive neoplasm of the mesothelium which is often associated with exposure to asbestos. "In mesothelioma cells, in vitro, FBLN1 also acts as tumor suppressor gene." (PMID 35932462, 2022).
myocardial infarction (2 papers, 2021 to 2022). Gross necrosis of the myocardium, as a result of interruption of the blood supply to the area, as in coronary thrombosis. "FBLN1 showed reduced serum concentrations in myocardial infarction." (PMID 34975707, 2021).
myopia (2 papers, 2010 to 2020). "Interactions between fibulin-1 and aggrecan may be important, and the modulation of aggrecan levels and distribution could play a key role in changing the scleral creep rate, which is associated with axial elongation of the eye and the development of myopia." (PMID 20405022, 2010). "Further studies on the role of fibulin-1 in the regulation of eye growth, including during the development of myopia, are therefore warranted." (PMID 20405022, 2010). "Further research on the function of fibulin-1 and its interaction with aggrecan in sclera during the development of myopia is warranted." (PMID 20405022, 2010).